MTLN (mitoregulin)
Description:
Positively regulates mitochondrial complex assembly and/or stability (By similarity). Increases mitochondrial membrane potential while decreasing mitochondrial reactive oxygen species. Increases mitochondrial respiration rate. Increased mitochondrial respiratory activity promotes myogenic differentiation which facilitates muscle growth and regeneration (By similarity). Increases mitochondrial calcium retention capacity. Plays a role in maintenance of cellular lipid composition through its interaction with cytochrome b5 reductase CYB5R3 which is required for mitochondrial respiratory complex I activity (By similarity). Interacts with the mitochondrial trifunctional enzyme complex (MTE) and enhances fatty acid beta-oxidation. Not required for MTE formation or stability (By similarity). Modulates triglyceride clearance in adipocytes through its role in regulating fatty acid beta-oxidation and lipolysis.
Synonyms: LEMP; LINC00116; MOXI; MPM; NCRNA00116; SMIM37; TILR
Tractability: Antibody: UniProt predicts a signal peptide or a membrane-spanning region. PROTAC: ubiquitination databases record sites on it.
Gene: Protein-coding gene on chromosome 2 (110,211,529 to 110,245,420, reverse strand). Ensembl gene ENSG00000175701.
Subcellular location: Mitochondrion inner membrane
Gene Ontology:
Molecular function: protein binding
Biological process: fatty acid beta-oxidation; mitochondrial respirasome assembly; triglyceride homeostasis; cellular respiration; lipid metabolic process; positive regulation of fatty acid beta-oxidation; positive regulation of mitochondrial membrane potential; striated muscle cell differentiation
Cellular component: mitochondrion; mitochondrial inner membrane
Homologues: Orthologues: pig MTLN (98% identical), dog MTLN (96% identical), mouse Mtln (95% identical), guinea pig MTLN (93% identical), rabbit MTLN (91% identical), tropical clawed frog MTLN (73% identical).
Diseases named in the same sentence as MTLN in open-access papers:
MTLN is named in the same sentence as 16 diseases in open-access papers, as found by Europe PMC text mining. Sharing a sentence is not in itself a finding about the gene and the disease. The quoted sentences say what the papers report.
hepatocellular carcinoma (2 papers, 2024). A malignant tumor that arises from hepatocytes. "MPM (micropeptide in mitochondria), also known as MOXI/MTLN, has recently been linked to cancer through its role in hepatocellular carcinoma metastasis." (PMID 39311199, 2024).
chronic kidney disease (1 paper, 2025). Impairment of the renal function secondary to chronic kidney damage persisting for three or more months. "For example, MTLN is upregulated in chronic kidney disease and promotes fibrosis." (PMID 40076565, 2025).
Insulin resistance (1 paper, 2025). Increased resistance towards insulin, that is, diminished effectiveness of insulin in reducing blood glucose levels. "Notably, the metabolic consequences of MTLN deficiency may vary, depending on the context, and certain dietary settings may mitigate rather than exacerbate insulin resistance." (PMID 41465308, 2025).
lung adenocarcinoma (1 paper, 2025). A carcinoma that arises from the lung and is characterized by the presence of malignant glandular epithelial cells. "In addition, lower MTLN expression in lung adenocarcinoma (LUAD) correlates with significantly improved patient survival." (PMID 40076565, 2025).
lung carcinoma (1 paper, 2025). "Through this investigation, we examined MTLN’s relationship with lung cancer, with a focus on the MTLN effects on A549 LUAD cell proliferation and sensitivity to inhibitors of hydroperoxide metabolism." (PMID 40076565, 2025). "We focused our investigation on lung cancer, and specifically on LUAD, for which MTLN gene expression is significantly increased compared to normal lung tissue (data acquired from the OncoDB website)." (PMID 40076565, 2025). "Though our study highlights a key role for MTLN in driving the proliferation of lung cancer cells, it does not exclude the possibility that MTLN is recruited to push cell cycle progression in other pathologies." (PMID 40076565, 2025). "These MTLN findings are consistent with and reinforce a previous report examining LINC00116 (MTLN) expression in a distinct cohort of 19 paired lung cancer and non-cancerous adjacent tissue." (PMID 40076565, 2025).
metabolic syndrome (1 paper, 2025). A cluster of metabolic risk factors for CARDIOVASCULAR DISEASES and TYPE 2 DIABETES MELLITUS. "For example, a deeper mechanistic understanding of how mitoregulin alters metabolic flux could inspire novel treatments for metabolic syndrome or help inhibit cancer cell growth by interfering with tumor-specific AltORFs." (PMID 41033461, 2025).
tumor (4 papers, 2021 to 2025). "With an interest in understanding how MTLN, as a mitochondrial microprotein, influences tumor cell survival in LUAD, we examined the effects of manipulating MTLN expression in the A549 NSCLC/LUAD cell line." (PMID 40076565, 2025).
cancer (3 papers, 2024 to 2025). A tumor composed of atypical neoplastic, often pleomorphic cells that invade other tissues. "Involvement of MTLN in promoting cell cycle progression in diseases apart from cancer is an intriguing area open to future examination." (PMID 40076565, 2025). "This coincides with a multitude of previous reports from us and others demonstrating MTLN residence in mitochondria in normal and/or cancer cells." (PMID 40076565, 2025). "Given the observed influence of MTLN in the key processes of cancer cells (ROS modulation, energy production, overall mitochondrial function), we began by examining the expression of MTLN across cancer types." (PMID 40076565, 2025). "To further investigate the involvement of MTLN in hydroperoxide metabolism, we tested the effect of BSO + AF anti-cancer drugs in the context of MTLN silencing." (PMID 40076565, 2025). "The continued discovery of novel players and vulnerable components, such as MTLN, has the potential to lead to the development of effective multi-hit approaches for cancer therapy." (PMID 40076565, 2025). "MTLN gene expression is elevated in most cancers, and for LUAD, we found that lower MTLN gene expression correlates with improved overall survival and prognosis." (PMID 40076565, 2025). "MTLN loss has been associated with changes in mitochondrial calcium, ER contacts, mitochondrial superoxide, fatty acid oxidation, retrograde JUN signaling, and lipid metabolism, all with the potential to influence cancer progression or sensitivity to anti-cancer drugs." (PMID 40076565, 2025). "As cancer datasets and data mining capabilities expand, acquiring such information could prove vital to understanding molecular mechanisms and tailoring of any MTLN-based therapeutics." (PMID 40076565, 2025). "Like MTLN, ROMO1 gene expression is elevated in many cancers." (PMID 40076565, 2025). "MTLN gene expression is elevated broadly across most cancers and has been proposed as a prognostic biomarker for non-small cell lung cancer (NSCLC)." (PMID 40076565, 2025). "Our findings do not rule out additional pathways through which MTLN may contribute to cancer cell biology." (PMID 40076565, 2025). "Using TNMplot, a web tool that plots mRNA expression across cancerous and non-cancerous tissues, it was evident that gene expression of MTLN was significantly higher in cancerous tissue compared to the neighboring non-cancerous tissue for most cancer types (14 of 22)." (PMID 40076565, 2025).
MTLN also shares sentences with these, for which no sentence is quoted: acute myeloid leukemia (1 paper); bladder cancer (1); breast carcinoma (1); Duchenne muscular dystrophy (1); multiple myeloma (1); muscular dystrophy (1); non-small cell lung carcinoma (1); tibial muscular dystrophy (1).